SHMT1 (serine hydroxymethyltransferase 1)
Diseases named in the same sentence as SHMT1 in open-access papers (continued):
Sharing a sentence is not in itself a finding about the gene and the disease.
ovarian carcinoma (7 papers, 2012 to 2025). A malignant neoplasm originating from the surface ovarian epithelium. "Collectively, these findings demonstrate that loss of SHMT1 results in decreased expression of the pro-oncogenic inflammatory cytokines IL-6 and IL-8, which in turn results in inhibition of ovarian cancer tumor growth." (PMID 28288142, 2017). "Similar to our results with ovarian cancer cells expressing SHMT1 shRNA, loss of N-acetylneuraminic acid synthetase resulted in reduced levels of IL-6 and IL-8." (PMID 28288142, 2017). "Several polymorphisms in the SHMT1 gene have been linked to a higher chance of cancer, like acute lymphoblastic leukemia, ovarian cancer and prostate cancer." (PMID 22292074, 2012). "Comprehensive gene expression analysis of HGSOC patient samples revealed that SHMT1 expression is significantly elevated in ovarian cancer." (PMID 40738465, 2025). "SHMT1 knockout significantly reduced colony formation on soft agar and diminished the migratory capacity of ovarian cancer cells in vitro." (PMID 40738465, 2025). "Mechanistically, SHMT1 promotes ovarian cancer metastasis and progression by increasing Neu5Ac levels and upregulating the proinflammatory cytokines including IL-6 and IL-8." (PMID 40738465, 2025). "High-grade serous (HGS) ovarian cancer research showed that SHMT1 can stimulate pro-oncogenic cytokine expression through sialic acid to promote tumor growth and progression." (PMID 37009511, 2023). "SHMT1 in ovarian cancer stimulated pro-oncogenic cytokine expression to promote tumor growth and progression." (PMID 30755243, 2019). "Third, SHMT1 promotes ovarian cancer tumor growth and progression, in part, by facilitating expression of pro-oncogenic inflammatory cytokines IL-6 and IL-8, and, at least in part, by regulating cellular levels of Neu5Ac." (PMID 28288142, 2017). "We found that Neu5Ac supplementation of culture medium stimulated IL-6 and IL-8 production and rescued the ability of ovarian cancer cells expressing SHMT1 shRNA to grow in an anchorage-independent manner and increased their migratory ability." (PMID 28288142, 2017). "To determine the effect of SHMT1 knockdown on expression of mRNAs of protein-coding genes in ovarian cancer cells, we performed global mRNA expression analysis in PEO4 ovarian cancer cells after SHMT1 knockdown." (PMID 28288142, 2017). "First, SHMT1 is necessary for ovarian cancer tumor growth and progression, and SHMT1 expression is regulated by transcription factor WT1." (PMID 28288142, 2017). "We found that expression of exogenous SHMT1 in WT1 shRNA-expressing ovarian cancer cells rescued the cells' ability to form colonies in soft agar." (PMID 28288142, 2017). "Supplementation of culture medium with Neu5Ac stimulated expression of IL-6 and IL-8 and rescued the tumor growth and migratory phenotypes of ovarian cancer cells expressing SHMT1 shRNAs." (PMID 28288142, 2017). "Addition of Neu5Ac resulted in increased levels of IL-6 and IL-8 mRNA and protein in ovarian cancer cells expressing SHMT1 shRNA." (PMID 28288142, 2017). "In this direction, we noticed some interesting candidates in our gene expression profiling data of ovarian cancer cells expressing SHMT1 shRNAs." (PMID 28288142, 2017). "In ovarian cancer, SHMT1 not only promotes tumor growth but also facilitates metastasis." (PMID 40738465, 2025). "We found that WT1 knockdown in ovarian cancer cell lines resulted in reduced SHMT1 expression." (PMID 28288142, 2017). "Based on our analysis of the TCGA data set, SHMT1 mRNA was upregulated in ovarian cancer samples." (PMID 28288142, 2017). "Second, in addition to the expected alterations in the metabolites of the folic acid metabolic pathway, SHMT1 knockdown in ovarian cancer cells unexpectedly resulted in downregulation of several metabolites of the amino sugar and nucleotide sugar metabolic pathway, including Neu5Ac." (PMID 28288142, 2017).
ovarian carcinoma (continued). "Similarly, SHMT1 knockdown inhibited the colony-forming ability of other ovarian cancer cell lines COV504 and COV413B in soft agar." (PMID 28288142, 2017). "In particular brain-derived neurotrophic factor (BDNF) and transcription factor activator protein-2α might be of interest for additional studies as potential mediators of ovarian cancer-promoting function of SHMT1." (PMID 28288142, 2017). "Here, by combining the TCGA ovarian cancer gene expression data set with the functional genomics approach of RNA interference, we demonstrated that the enzyme serine hydroxymethyl transferase 1 (SHMT1) is necessary for ovarian cancer tumor growth and progression." (PMID 28288142, 2017). "SHMT1 knockdown has the potential to inhibit PEO4 cell growth, and inhibits the colony-forming ability of other ovarian cancer cell lines, COV504 and COV413B, in soft agar." (PMID 40738465, 2025). "We found that, similar to SHMT1 knockdown, WT1 knockdown also prevented the ability of ovarian cancer cells to form colonies in soft agar." (PMID 28288142, 2017). "SHMT1 promoter analysis identified transcription factor Wilms tumor 1 (WT1) binding sites, and WT1 knockdown resulted in reduced SHMT1 transcription in ovarian cancer cells." (PMID 28288142, 2017). "To determine if SHMT1 loss-mediated downregulation of IL-6 and IL-8 also occurs in other ovarian cancer cell lines, we measured IL-6 and IL-8 mRNA levels in other ovarian cancer cell lines COV504 and COV413B expressing SHMT1 shRNA and observed similar results." (PMID 28288142, 2017). "We find that knockdown of SHMT1 results in reduced BDNF expression and increase in transcription factor activator protein-2α expression in ovarian cancer cells." (PMID 28288142, 2017). "Thus, targeting of SHMT1 and Neu5Ac represents a precision therapy opportunity for effective HGS ovarian cancer treatment." (PMID 28288142, 2017). "We found that SHMT1 knockdown did not inhibit invasion of ovarian cancer cells, but did result in significant reduction in the ability of ovarian cancer cells to migrate, as demonstrated by impaired wound healing in cells expressing SHMT1 shRNAs compared with cells expressing nonspecific shRNAs." (PMID 28288142, 2017). "Additionally, transcriptome-wide mRNA expression analysis of ovarian cancer cells lacking SHMT1 revealed reduced IL-6 and IL-8 mRNA levels." (PMID 28288142, 2017). "To determine if loss of SHMT1 effects ovarian cancer tumor growth in vivo, we injected ovarian cancer cell lines expressing either shRNA targeting SHMT1 or a nonspecific shRNA subcutaneously into the flanks of the athymic nude mice and measured tumor volume at specific time points after injection." (PMID 28288142, 2017).
prostate carcinoma (7 papers, 2011 to 2025). A carcinoma that arises from epithelial cells of the prostate gland. "In prostate cancer, SHMT1 has been implicated in metabolic rewiring and may be involved in coordinating 1-carbon flux alongside other metabolic enzymes." (PMID 40738465, 2025). "To date, no direct mechanistic studies have been conducted to assess the impact of SHMT1 on tumor growth, survival, or clinical outcomes in prostate cancer." (PMID 40738465, 2025). "An analysis of TCGA prostate cancer cohort (n = 498) reported SHMT1 dysregulation in approximately 5% of tumors, mainly through elevated mRNA expression." (PMID 40738465, 2025). "Collectively, these studies suggest that SHMT2 may exert stage-specific effects on prostate cancer progression and metastasis, while the role of SHMT1 in this process remains largely unexplored." (PMID 40738465, 2025). "In LASCPC-01 cells, higher expression levels of genes encoding SHMT1 and SHMT2 and decreased availability of serine and glycine has been observed, indicating a higher demand of serine and glycine for multiple purposes in this aggressive subtype of prostate cancer." (PMID 31035489, 2019).
colon cancer (6 papers, 2010 to 2024). "In contrast with colon cancer, the adjusted risk ratio for rectal cancer was significantly lower for SHMT1 TT and higher for MTHFR CT genotypes." (PMID 20920350, 2010). "The aim of our study was to separately analyze the risk of rectal and colon cancer in association with SHMT1 C1420T and MTHFR C677T polymorphisms." (PMID 20920350, 2010). "Association between rectal or colon cancer risk and serine hydroxymethyltransferase 1 (SHMT1) C1420T or methylenetetrahydrofolate reductase (MTHFR) C677T polymorphisms was assessed." (PMID 20920350, 2010). "Dual SHMT1/2 knockout blocked HCT-116 colon cancer xenograft formation, suggesting that both SHMT1 and 2 may be involved in the association between serine metabolic reprogramming and lymphoma." (PMID 37664062, 2023). "which showed that HCT116 colon cancer cells, engineered with mitochondrial 1C enzyme deletions, form xenograft tumours by generating cytosolic 1C units from serine via the enzyme SHMT1." (PMID 38431691, 2024). "Considering the ability of 2.12 to preferentially inhibit human SHMT1, we treated lung and colon cancer cell types with this compound and studied the induction of cell death." (PMID 26717037, 2016). "A protective effect of SHMT1 1420T allele or SHMT1 1420 T allele/MTHFR 677 CC diplotype against rectal but not colon cancer risk was demonstrated." (PMID 20920350, 2010). "In his study only male cases and male hospital-based controls were used from Caucasian-American populations, but the rectal and colon cancer patients were not separately analyzed, thus the risk modifying effect of the SHMT1 C1420T polymorphism might be obscured." (PMID 20920350, 2010). "The SHMT1 and MTHFR genotypes were determined by real-time PCR and PCR-RFLP, respectively in 476 patients with rectal, 479 patients with colon cancer and in 461 and 478, respective controls matched for age and sex." (PMID 20920350, 2010). "In our study both investigated polymorphisms, SHMT1 C1420T and MTHFR C677T, exert influence on the risk of rectal but not on that of colon cancer." (PMID 20920350, 2010). "Homocysteine could be considered as a tumor marker in SHMT1 1420 wild-type (CC) CRC patients in Dukes' stage C and D. Further studies need to clarify why SHMT1 and MTHFR polymorphisms are associated only with rectal and not colon cancer risk." (PMID 20920350, 2010).
acute lymphoblastic leukemia (5 papers, 2010 to 2024). Leukemia with an acute onset, characterized by the presence of lymphoblasts in the bone marrow and the peripheral blood. "Studies have also been carried out to examine the associations of SHMT1 with the development of acute lymphoblastic leukemia, tumors, neural tube defects, and sclerotic changes." (PMID 35098008, 2021). "Lack of SHMT1 function is, among other effects, associated with acute lymphocytic leukemia." (PMID 27386562, 2016). "Targeting both SHMT1 and SHMT2 together was recently shown to be more effective in T-cell acute lymphoblastic leukemia (T-ALL) therapy, and the inhibitors working on both SHMT1 and 2 were sensitive on methotrexate-resistant cell lines as well." (PMID 39189649, 2024).
folate deficiency (5 papers, 2018 to 2024). A nutritional condition produced by a deficiency of FOLIC ACID in the diet. "In a state of folate deficiency, the aberrant activation of serine hydroxymethyltransferase 1 (SHMT1) disrupts thymidylate biosynthesis, potentially resulting in cognitive dysfunction." (PMID 38999809, 2024). "SHMT1 has been shown to directly interfere with folate metabolism and its loss leads to folate deficiency, sensitizing embryos to neural tube defects." (PMID 36627750, 2023). "In the present study, we further discovered that shMTHFR promoted the expression and translocation of SHMT1/DHFR/TYMS complex in the nucleus during folate deficiency." (PMID 34502300, 2021). "Conditions of folate deficiency further impose a requirement for serine-dependent generation of 5,10-methylene THF by the action of SHMT1, acting in the cytoplasm and/or nucleus." (PMID 31636139, 2019). "Uracil in DNA results from impaired de novo dTMP synthesis, which is caused either by folate deficiency or lack of SHMT1." (PMID 29955725, 2018).
hepatocellular carcinoma (5 papers, 2021 to 2025). A malignant tumor that arises from hepatocytes. "SHMT1 affects the expression of downstream molecules ROS through NOX1 in hepatocellular carcinoma, leading to the production of EMT and MMP2 and ultimately influencing its proliferation." (PMID 38594513, 2024). "The role of SHMT1 in hepatocellular carcinomas is still unclear, although some recent studies revealed a significantly decreased expression of SHMT1." (PMID 35201488, 2021). "Therefore, we speculate that SHMT1 deficiency may increase the risk of MASLD progression to liver fibrosis and even hepatocellular carcinoma (HCC)." (PMID 40738465, 2025). "C-MYC directly controls the transcription of PHGDH, PSAT1, PSPH, SHMT1, and SHMT2 in human hepatoma and HeLa cells." (PMID 37949226, 2023).
acute leukemia (4 papers, 2013 to 2025). A clonal (malignant) hematopoietic disorder with an acute onset, affecting the bone marrow and the peripheral blood. "Additionally, the C1420T polymorphism in SHMT1 has been linked to increased susceptibility to childhood acute leukemia, suggesting a broader role for SHMT1 in DNA metabolism-related pathologies." (PMID 40738465, 2025). "Although acute leukemias are typically highly proliferative, the effect of one-carbon folate pathway inhibition using a novel inhibitor of SHMT1 and SHMT2, RZ-2994, was greater in T-ALL compared to AML." (PMID 34341479, 2022).
ischemic stroke (4 papers, 2011 to 2025). A stroke disorder caused by obstruction of blood flow to the brain, due to thrombotic (local blood clot formation) or embolic (due to a blood clot or other material traveling from another site) event. "Our results showed that the plasma Hcy concentration was much higher in ischemic stroke patients and was significantly associated with SHMT1 methylation." (PMID 33259775, 2021). "Multivariable logistic regression analysis of association between SHMT1 methylation and the risk of ischemic stroke." (PMID 33259775, 2021). "Moreover, the HDL concentration was lower in the ischemic stroke patients and the SHMT1 methylation levels were associated with HDL concentration in controls." (PMID 33259775, 2021). "SHMT1 variants may be involved in Hcy metabolism and, therefore, contribute to an increased risk of ischemic stroke." (PMID 33259775, 2021). "In the present study, we explored the association between SHMT1 methylation and ischemic stroke." (PMID 33259775, 2021). "SHMT1 rs11868708 risk allele conferred a 1.46-fold risk of ischemic stroke in Singaporean Chinese." (PMID 27822905, 2017). "Therefore, we hypothesized that DNA methylation of SHMT1 would be associated with ischemic stroke case–control status." (PMID 33259775, 2021). "Moreover, SHMT1 expression was shown to be associated with phosphate-induced vascular smooth muscle cell calcification and a SHMT1 variant was suggested as a risk factor in early-onset ischemic stroke." (PMID 33259775, 2021). "Its increase in the present study aligns with the literature that found ischemic stroke patients exhibit significantly higher SHMT1 promoter methylation compared to healthy controls, which is strongly associated with elevated plasma homocysteine levels." (PMID 40950018, 2025). "This study aimed to determine the correlation between serine hydroxymethyl transferase 1 (SHMT1) gene methylation and ischemic stroke." (PMID 33259775, 2021). "A significantly higher level of SHMT1 methylation was observed in the ischemic strokes (58.82 ± 17.83%) compared to that in the controls (42.59 ± 20.76%, p < 0.001)." (PMID 33259775, 2021). "The purpose of this study was to determine the correlation between SHMT1 gene methylation and ischemic stroke in a Chinese population." (PMID 33259775, 2021). "We also identified the effects of SHMT1 methylation on Hcy and circulating lipids in ischemic stroke patients." (PMID 33259775, 2021). "Our results showed that the methylation levels of SHMT1 were much higher in ischemic stroke patients than in healthy controls." (PMID 33259775, 2021). "The total number of risk alleles on MTRR rs16879248, SHMT1 rs11868708, TCN2 rs1173570 showed a cumulative effect on ischemic stroke." (PMID 27822905, 2017). "The ROC analysis of curve showed that SHMT1 methylation had acceptable diagnostic value for ischemic stroke regardless of sex (area under the curve [AUC] = 0.71, p < 0.001; male patients, AUC = 0.62, p = 0.032; and female patients, AUC = 0.79, p < 0.001)." (PMID 33259775, 2021). "The SHMT1 methylation level was strongly correlated with HDL concentration in the healthy controls (r = 0.517, p < 0.001), while the high plasma level of Hcy showed strong association with SHMT1 methylation in ischemic strokes (r = 0.346, p < 0.001)." (PMID 33259775, 2021). "Our results showed that SHMT1 methylation levels were associated with ischemic stroke in both sexes, regardless of age." (PMID 33259775, 2021). "In contrast, the plasma level of Hcy showed strong association with SHMT1 methylation in ischemic stroke patients (r = 0.346, p < 0.001), but not in controls (r = 0.037, p = 0.715, Spearman’s test)." (PMID 33259775, 2021). "Our study suggested that deficiency of both folate and vitamin B12 levels, caused by a combination of genetic variations at SHMT1, MTRR and TCN2, may jointly increase ischemic stroke risk." (PMID 21935458, 2011).
ischemic stroke (continued). "In addition, ROC analysis suggested that SHMT1 methylation may be a useful predictor for female ischemic stroke." (PMID 33259775, 2021). "SNP analysis from the initial study suggested 3 risk variants in the MTRR, SHMT1 and TCN2 genes which were moderately associated with ischemic stroke risk, independent of known stroke risk factors." (PMID 21935458, 2011).
non-small cell lung carcinoma (4 papers, 2020 to 2025). A group of at least three distinct histological types of lung cancer, including non-small cell squamous cell carcinoma, adenocarcinoma, and large cell carcinoma. "The SHMT1-targeted inhibitor AGF347, a novel pyrrolo [3,2-d] pyrimidine compound, shows anti-tumor efficacy in HCT116 colon cancer, H460 non-small cell lung cancer (NSCLC), and MIA PaCa-2 pancreatic cancer." (PMID 35531073, 2022).
gastric cancer (3 papers, 2010 to 2024). A primary or metastatic malignant neoplasm involving the stomach. "In a recent study an interactive influence of MTHFR C677T and SHMT1 C1420T polymorphisms in the risk of esophageal and gastric carcinomas was also observed." (PMID 20920350, 2010). "The homozygous mutant genotype of the rs1979277 (SHMT1) variant was indicated to be associated with an increased risk of toxicity in a study assessing fluoropyrimidine and platinum-based therapy-induced toxicity in gastric cancer patients." (PMID 39592679, 2024).
head and neck cancer (3 papers, 2017 to 2021). A primary or metastatic malignant neoplasm affecting the head and neck. "Here, we aimed to investigate the association of polymorphisms DNMT3B -149C/T (rs2424913), DNMT3B -283T/C (rs6087990), DNMT3B -579G/T (rs2424909), DHFR 19-pb ins/del (rs70991108), SHMT1 1420C/T (rs1979277), and TYMS 28-bp tandem repeat (rs34743033) with the risk of head and neck cancer." (PMID 33369477, 2020).
intestinal cancer (3 papers, 2015 to 2025). "Shmt1+/− mice accumulate uracil within nuclear DNA and show increased susceptibility to neural tube defects and intestinal cancer." (PMID 26103880, 2015).